IDO1 (indoleamine 2,3-dioxygenase 1)
Diseases named in the same sentence as IDO1 in open-access papers (continued):
Sharing a sentence is not in itself a finding about the gene and the disease.
cancer (continued). "Cancer cells use indoleamine 2,3-dioxygenase 1 (IDO1) pathway to suppress the host's immune response in order to facilitate survival, growth, invasion, and metastasis of malignant cells." (PMID 27578919, 2016). "Here, we observed that discrete tumoral IDO1 expression pattern was dominant in patients with hepatocelluar carcinomas." (PMID 26895379, 2016). "Numerous preclinical studies have subsequently documented the therapeutic potential of IDO1 inhibitors in cancer therapy, either alone or in combination with chemotherapy or immunotherapy." (PMID 25691885, 2015). "Based on the enzyme’s immunosuppressive functions, IDO1 is becoming established as a target for drug discovery in cancer immunotherapy." (PMID 26378585, 2015). "Studies on human cancer cells have shown that KYN activates the AhR-ARNT associated transcription of IL-6, which induced autocrine activation of IDO1 via STAT3." (PMID 26881062, 2015). "In line with their immunosuppressive phenotype, several molecules, known to be linked to cancer progression and immune evasion, were highly expressed (>80%: CD47, CD274, CD276, and Indoleamine 2,3 dioxygenase-1)." (PMID 26618628, 2015). "This is a particular need, since a recent study found that IDO-1 expression was paradoxically upregulated in human cancers from 1-D-MT, a compound currently used in a phase 2 clinical study in patients with metastatic breast cancer." (PMID 25415278, 2014). "IDO1 acts to control the activation and differentiation of T regulatory cells (Treg) in a variety of settings, including cancer." (PMID 25477879, 2014). "Indoleamine 2,3-dioxygenase-1 mediates tolerance against tumors, and IDO inhibitors are being tested in clinical trials with patients suffering from cancer and chronic infections." (PMID 24904580, 2014). "While first clinical trials with IDO1 inhibitors are underway, this review aims at putting the recent advances in understanding the immunobiology of TRP catabolism via IDO1/TDO in therapeutic perspective for cancer immunotherapy." (PMID 25628622, 2014). "From RNAseq data of the 23 cancers in our study, we found a significant correlation between IDO1 expression and kynurenine levels (r = 0.55, P = 0.01)." (PMID 25091696, 2014). "Indoleamine 2,3-dioxygenase 1 (IDO1) has become a recognized mediator of immune tolerance in cancer-bearing hosts, promoting local metabolic changes that affect cellular and systemic responses to inflammatory and immunological signals." (PMID 23973990, 2013). "Upregulation of IDO1 by 1-D-MT in many cancer cells was most prominent at moderate concentrations of IFN-γ that are likely to resemble physiological concentrations." (PMID 21625531, 2011). "After stimulation with appropriate IFN-γ concentrations, 1-D-MT increased IDO1 mRNA and kyn production in a panel of different cancer cells, indicating a universal mechanism of 1-D-MT-mediated activation of IDO1." (PMID 21625531, 2011). "Here we show that proliferation of alloreactive T-cells cocultured with IDO1-positive human cancer cells paradoxically was inhibited by 1-D-MT." (PMID 21625531, 2011). "Investigation of the underlying mechanisms surprisingly revealed that 1-D-MT increased the kyn production of cancer cells with IDO1 activity due to upregulation of IDO1 mRNA and protein expression." (PMID 21625531, 2011). "The upregulation of IDO1 expression and activity was observed only in cancer cells with either constitutive or IFN-γ-induced IDO1 expression." (PMID 21625531, 2011). "In cancer, IDO1 acts as an immune checkpoint, suppressing effector T cell function." (PMID 41823303, 2026). "This unique mechanism of action may open up alternative therapeutic opportunities for the treatment of cancer beyond classical inhibition of IDO1." (PMID 41501556, 2026).
cancer (continued). "Notably, the upregulation of these inflammatory factors and Ido1 was more pronounced in immune cells than in both human and murine cancer cells, suggesting that immune cells are the primary responders to the STING agonists in this context." (PMID 41129257, 2025). "In contrast, IDO1 degradation would eliminate both, enzymatic activity and signaling function, and may open up new opportunities for the treatment of cancer or, as recent studies imply, the treatment of diseases related to Epstein Barr virus infections." (PMID 39026748, 2025). "The usefulness of IDO-1 inhibition as a strategy to enhance anti-PD-1 therapy activity in cancer remains unclear." (PMID 40475772, 2025). "As another example, the metabolism of kynurenine—a byproduct of tryptophan catabolism resulting from the high expression of indoleamine 2,3-dioxygenase 1 (IDO1) in cancer cells—has been shown to suppress the cytotoxic functions of CD8+ T cells, ultimately leading to T-cell exhaustion." (PMID 40830700, 2025). "These inhibitors could affect pro-tumorigenic IDO1 signaling, and synergistic combinations with IDO1 catalytic inhibitors should be tested in cancer immunotherapy." (PMID 41262240, 2025). "The expression of IDO1 in cancer stem cells is stimulated by IFN-γ from T cells." (PMID 40365295, 2025). "Finally, kynurenine is a PTM often dysregulated in cancer due to overactivation of the tryptophan–kynurenine pathway, driven by increased expression of enzymes like IDO1, TDO, and KYN2." (PMID 40239839, 2025). "Besides IL-6, cancer cell–secreted Wnt5a induces IDO1 expression through β-catenin (CTNNB1) activation in DCs." (PMID 40789452, 2025). "In addition, a combination of IFN-γ treatment with IDO-1 inhibitors is a promising new immunotherapeutic strategy in cancer treatment." (PMID 40710094, 2025). "Among other genes that encode immune inhibitors, IL10, TGFBR1, and IDO1 exhibited a broadly negative correlation across most cancer types, aligning with the expression pattern of PEBP1/STK11." (PMID 40806276, 2025). "In cancer compartment, IDO1 displayed few alterations in approximately twenty different tumors." (PMID 40287406, 2025). "In addition, enrichment analysis identified links to metabolic pathways such as glycolysis and fatty acid metabolism, as well as pathways involved in cancer immune evasion (e.g., IDO1 activity and effector T cell suppression)." (PMID 41402667, 2025). "The IDO1 inhibitor LY3381916 is undergoing phase I clinical trials in advanced cancers." (PMID 41332472, 2025). "Consequently, the effectiveness of IDO1 inhibition as a strategy to enhance the activity of anti-PD-1 therapy in cancer remains uncertain." (PMID 40075563, 2025). "This unique mechanism of action may open up new therapeutic opportunities for the treatment of cancer beyond classical inhibition of IDO1." (PMID 39026748, 2025). "To determine whether the anticancer effects of 7k were mediated through AhR inhibition, we evaluated the expression of AhR downstream targets, including AhR, AhRR, and IDO-1, in kynurenine-stimulated cancer cells using qPCR analysis." (PMID 41155994, 2025). "In most forms of human cancers, high IDO1 expression is positively correlated with poor prognosis." (PMID 40512849, 2025). "The heme level in IDO1 directly determines its production of L-Trp metabolites that govern the immune response and other processes, including blood pressure regulation, emotional state, and cancer progression." (PMID 40609793, 2025). "A pan‐cancer analysis using TCGA and GTEx data revealed that IDO1 is highly expressed in BLCA." (PMID 41438182, 2025). "Strikingly, ACACA expression exhibited significant negative correlations with the immune checkpoint-related genes (PDCD1, LAG3, LAGLS9, IDO1, CD244, CTLA4 and TIGIT), while showing positive associations with other genes (TGFBR1, KDR, IL10RB, CD160 and CD274) across most cancer types." (PMID 41169354, 2025). "IDO1 is another protein silencing immune responses in cancer." (PMID 39061159, 2024).
cancer (continued). "IDO1 and TDO2 expression are associated with numerous tolerogenic immune cells, including suppression of effector T cells and infiltration of MDSCs and Tregs in multiple cancer types." (PMID 38339226, 2024). "Thus, there is a need to better understand the landscape of IDO1 in cancers and relationship of IDO expression to immunotherapy outcome." (PMID 38632994, 2024). "Therefore, extensive research has been conducted on IDO1 inhibitors through clinical trials to explore their potential for enhancing cancer immunotherapy." (PMID 38780888, 2024). "Cancer cells can constitutively express IDO1, but IDO1 on immune cells is IFN inducible." (PMID 38831013, 2024). "Thus, inhibiting AHR activity represents an exciting therapeutic strategy to target multiple cancer dependencies by blocking kynurenine signaling downstream of IDO1 and TDO2." (PMID 39450255, 2024). "Moreover, immunohistochemical analysis and qRT-PCR were used to evaluate IDO1’s expression in pan-cancer cells." (PMID 38539263, 2024). "However, small-molecule inhibitors such as epacadostat can block IDO1 activity and restore anti-tumoral T cell immunity in mice, in synergy with immune checkpoint inhibitors or cancer vaccines." (PMID 40809135, 2024). "Several studies have demonstrated that IDO1 is highly expressed in multiple types of human cancer." (PMID 39064305, 2024). "Furthermore, across a variety of cancer types, the aberrant IDO1 expression was connected to the TMB, MSI, MMR, medication sensitivity, and TIME." (PMID 38539263, 2024). "Serine is the main substrate of one-carbon units for nucleotide synthesis in vivo, however, in cancer cells with high expression of indoleamine 2, 3-dioxygenase 1(IDO1), tryptophan could replace serine as the main substrate of one-carbon units." (PMID 38238756, 2024). "However, other Trp-degrading enzymes, TDO and IDO1, have also been found on cancer cells, pointing to their role in facilitating the immune escape of tumors." (PMID 39337426, 2024). "Both FOXP3 and IDO1 had increased expression in cancer, further indicating T-cell suppression." (PMID 39672307, 2024). "IDO1’s function in human pan-cancers hasn’t been thoroughly studied, though." (PMID 38539263, 2024). "Therefore, based on the recent observations, the in-depth rewiring of IDO1 in cancer immunology is urgently needed to develop innovative and effective IDO1-targeted therapies against cancer." (PMID 38333210, 2024). "Expression of IDO1 was elevated in precancer and cancer as compared to controls." (PMID 39672307, 2024). "IDO1 is a heme-containing enzyme, and its heme levels are regulated by nitric oxide, suggesting that it is a potential prognostic indicator in various cancers." (PMID 39273017, 2024). "Since IDO1's role in immune tolerance has been unveiled, piles of studies have focused on its role in cancer immunology, leading to underappreciation of the impacts of IDO1, the rate‐limiting enzyme involved in essential amino acid metabolism, on lipid and glucose metabolism." (PMID 38706741, 2024). "IDO1 is a catabolic enzyme that converts tryptophan (Trp) into kynurenine in peripheral tissues and is an immune-checkpoint molecule that is highly expressed in many cancers." (PMID 38736462, 2024). "Cancer cells overexpress IDO1 which suppresses T cell effector function and promotes Tregs." (PMID 38539263, 2024). "In severe cases of cancer, overexpression of IDO1 leads to poor survival." (PMID 38539263, 2024). "Based on this knowledge, IDO1 has been considered a therapeutic target, and several inhibitors have been designed aiming to block its catalytic activity, restore immune system function, and improve cancer immunotherapy outcomes." (PMID 39594642, 2024). "Therefore, the mechanism behind IDO-1 signaling in cancer remains to be further investigated as IDO-1 has been associated strongly with ascites and survival of EOC patients." (PMID 39376560, 2024).
cancer (continued). "On that basis, it was hypothesised that dual IDO1/TDO2 inhibition may offer improved efficacy in many cancers, especially in those that commonly over-express TDO2." (PMID 39048947, 2024). "IDO1 is considered as an immune regulator that plays a pivotal role in numerous diseases such as central nervous system disorders, infections, autoimmune and inflammatory diseases, and cancers." (PMID 38564046, 2024). "Ccr7+Ido1+ DCs within the immunity hubs identified in our current study not only showed expression similarity with CCR7+LAMP3+IDO1+CD274+ activated DCs or mregDCs identified in human cancers, but also showed similar spatial co-localization with CD4+ and CD8+ T cells." (PMID 39414763, 2024). "Furthermore, targeting IDO1 in combination with immune checkpoint inhibitors has been proposed as a novel therapeutic approach for human cancers." (PMID 39273017, 2024). "GEO data (GSE35261, GSE30784, GSE26549, and GSE85195 combination), including 56 normal tissues, 78 OLKs, and 212 OSCCs, revealed a higher expression of IDO1 in OLK and OSCC than in para-cancer tissue and a positive relationship between IDO1 and CD68 expression in OLK." (PMID 39239507, 2024). "Nonetheless, a number of phase I and II trials has also been initiated since the failure of ECHO-301, suggesting that IDO1 inhibition may still have a future as an immunotherapeutic approach for cancer treatment." (PMID 39211039, 2024). "Therefore, IDO1 inhibition has been revealed as a promising approach to rewire immune surveillance towards cancer cells." (PMID 38591056, 2024). "The function of IDO1 in cancer is thought to be related to its immunosuppressive properties." (PMID 39064305, 2024). "IHC analysis showed that IDO1 expression is significantly increased in inflamed tissue compared to normal colon and this increased expression persists through to the development of cancer." (PMID 39242821, 2024). "In conclusion, ubiquitination/deubiquitination as one of the mechanisms regulating post-translation modifications of IDO1 holds promise as a therapeutic target for cancer and has potential for combination therapy with ICB, but further in vivo experiments are needed for its validation." (PMID 39253578, 2024). "In addition to its role in organ transplantation, IDO1 has also been extensively studied in the context of cancer." (PMID 39064305, 2024). "Some immunosuppressive factors secreted by cancer cells, such as indoleamine 2,3-dioxygenase 1 (IDO1) and tryptophan 2,3-dioxygenase 2 (TDO2), could suppress functional NK cells mediated ADCC." (PMID 39482550, 2024). "Targeting the IDO1 pathway has emerged as a promising therapeutic strategy in cancer immunotherapy." (PMID 39064305, 2024). "Furthermore, kynurenine, which is produced in excess by cancer cells due to IDO1, tryptophan 2,3-dioxygenase, and adenosine, which are derived from dead cancer cells, are suppressive metabolic products released from cancer cells." (PMID 39769351, 2024). "To evaluate IDO1 expression, we first performed transcriptomic expression evaluation on 514 metastatic/advanced tumors at the University of California San Diego Moores Cancer Center." (PMID 38632994, 2024). "IDO1 can be induced in various human cancer cells or immune cells by IFN-γ stimulation." (PMID 38540186, 2024). "In this study, we combined The Cancer Genome Atlas (TCGA) and Genotype-Tissue Expression (GTEx) to investigate abnormal expression and to assess its prognostic value in multiple cancer types, providing a comprehensive picture of the prognostic value and alteration of the IDO1 gene in pan-cancer." (PMID 38539263, 2024). "Also, there are not enough experiments to support this, a larger sample size is needed to validate the role and mechanism of IDO1 in pan-cancer." (PMID 38539263, 2024). "Of the carcinomas, 94% expressed IDO1, and 86% had sparse TILs consistent with cold tumors." (PMID 39061522, 2024). "Elevated levels of IDO1 correlate with reduced survival in patients with cancer." (PMID 37087488, 2023).
cancer (continued). "Besides MDSCs, IDO1 has been found expressed in mature DC, as well as in macrophages, cancer, endothelial and stromal cells in ccRCC." (PMID 37189689, 2023). "Programmed cell death protein 1 (PD-1)–programmed death-ligand 1 (PD-L1) interactions are inhibitory signals regulating immune responses, and in cancer, expression of PD-1/PD-L1 or indoleamine 2, 3-dioxygenase 1 (IDO1) allows for an escape from immune surveillance." (PMID 37367586, 2023). "Here, we summarize the recent advances in this field, focusing on IDO1 and IL4i1 in cancer." (PMID 37196768, 2023). "The tryptophan-kynurenine pathway and IDO1 have been recognized as pivotal mechanisms in immune escape of cancer, and inhibition of the latter might be a promising cancer treatment strategy." (PMID 37256178, 2023). "Interestingly, IDO1 is highly expressed in different cancer cell types, therefore IDO1 inhibitors were proposed as a potential therapeutic approach for the treatment of cancer." (PMID 37190141, 2023). "For this reason, several reports suggest that inhibition of CXCR-2 or IDO-1 may be therapeutically helpful in many human cancers." (PMID 37626777, 2023). "Furthermore, IDO1 has been confirmed to promote cancer metastasis in gastric cancer and hepatocellular carcinoma." (PMID 36983678, 2023). "BMS-986205 occupies the heme cofactor binding site to prevent the further activation of IDO1, thereby reversing the immunosuppression system in cancer patients, potentially improving cancer prognosis, especially when used in combination with other immunotherapies." (PMID 37509627, 2023). "The results of the association between IFN-γ score and ICG indicated that the IFN-γ scores of virtually all of the different cancers that were investigated had a positive association with the expression of TIGIT, IDO1, ICOS, CD86, CTLA4, HAVCR2, PDCD1LG2, and CD48." (PMID 37646041, 2023). "For these reasons, IDO1 is consequently thought to be a possible cancer immunological checkpoint." (PMID 37189689, 2023). "Additionally, the fact that Navoximod has already been successfully used in our group for cancer therapy also added to the confidence in our decision to choose Navoximod over other IDO-1 inhibitors for the HSV-1 combinatorial virotherapy." (PMID 37296221, 2023). "Several IDO1 and AhR inhibitors are now in clinical trials as potential cancer therapies." (PMID 37744363, 2023). "Therefore, inhibitors targeting IDO1 are recognized as a promising direction for cancer immunotherapy." (PMID 37903782, 2023). "Since most human cancers, including BC, overexpress indoleamine 2,3 dioxygenase 1, indoleamine 2,3 dioxygenase inhibitors could be used clinically in enhancing antitumor immunity." (PMID 37367861, 2023). "Epacadostat is the most investigated IDO1 inhibitor in cancer." (PMID 37456260, 2023). "However, increasing evidence shows that cancer patients cannot benefit from the treatment of IDO1 inhibitors alone or in combination with ICBs." (PMID 37655051, 2023). "Moreover, we investigated the levels of Kyn and Trp in serum as surrogate for IDO1 activity to examine the suitability of IDO1 activity as potential biomarker for cancer stage and therapy response." (PMID 35963900, 2023). "Thus, at this point, IDO-1 can be a potentially effective treatment target for both cancers, but further research is clearly needed to determine the validity of these initial findings." (PMID 37181043, 2023). "Furthermore, the IDO1/TDO2-AhR signaling pathway endows cancer cells with the capacity for evading immune surveillance and escaping immune responses." (PMID 37241719, 2023). "This provides a novel link between IL4i1- and IDO1-positive TMEs and cancer cell survival." (PMID 37196768, 2023). "IDO1 targeting has emerged as a novel therapeutic opportunity in modern cancer immunotherapy." (PMID 36959545, 2023). "The combination of IDO1 effects thus allows these cancer cells to escape immune targeting." (PMID 37444521, 2023).